AR (androgen receptor)
Diseases named in the same sentence as AR in open-access papers (continued):
Sharing a sentence is not in itself a finding about the gene and the disease.
prostate carcinoma (continued). "Our earlier studies defined a mechanistic model for male hormone dependent regulation of AR protein levels in prostate cancer (CaP) cells through a negative feed-back loop between AR and PMEPA1, an androgen induced NEDD4 E3 ubiquitin ligase binding protein." (PMID 25883222, 2015). "Taken together, our findings reveal a tumor suppressive mechanism for AR/miR-190a/YB-1 negative feedback loop in prostate cancer progression." (PMID 26314494, 2015). "HMGN2P46 is a pseudogene that is strongly expressed in AR-expressing prostate cancers but not expressed in AR-negative cancers in our cohort, suggesting an androgen regulated promoter." (PMID 25749039, 2015). "Based upon the physical interaction of CXCR7-SBP with AR in C7-SBP cells, we speculate that AR and CXCR7 protein levels might be regulated through protein-protein interactions mediated between AR and CXCR7 in androgen-sensitive prostate-cancer cells." (PMID 25884570, 2015). "Androgen receptor (AR), a ligand dependent transcription factor plays pivotal role in the development and progression of prostate cancer (PCa), the most frequently diagnosed non-cutaneous male malignancy." (PMID 25605250, 2015). "We tested the putative AR–HES6 and AR–ERG–HES1–HES6 transcriptional networks in AR-positive prostate cancer cells with and without TMPRSS2–ERG gene fusions (VCaP and LNCaP, respectively)." (PMID 25560400, 2015). "To better clarify the implications of MLT from its secondary effect on androgen levels, and the interferences of hyperglycemia and AR expression, we examined MLT influence on cell proliferation of human prostate epithelium cells and prostate cancer cell lineages." (PMID 26295055, 2015). "Castration-resistant (CR) prostate cancer (PCa) partly arises due to persistence of androgen receptor (AR) transcriptional activity in the absence of cognate ligand." (PMID 26310125, 2015). "In VCaP cells, a human prostate cancer cell line overexpressing both AR and the TMPRSS2-ERG gene fusion, an androgen response element (ARE)-targeted Py-Im polyamide significantly downregulates AR driven gene expression." (PMID 26571387, 2015). "Critically, we observed that low AR levels in cancer stroma, but not BPH stroma, were associated with prostate cancer related death (p=0.02) at censure, which was a minimum five years post initial diagnosis." (PMID 25965833, 2015). "In AR- prostate cancer PC-3 cells that do not express TRPM8, ectopic expression of TRPM8 showed inhibitory effect on cellular proliferation." (PMID 26512697, 2015). "Additionally, VCaP cells belong to a subtype of prostate cancer that possesses the TMPRSS2:ERG fusion, resulting in the AR driven expression of ERG." (PMID 26571387, 2015). "Again, the interaction between AR and ELK1 signals has been studied in prostate cancer cells." (PMID 26342199, 2015). "These cells were chosen as a model of androgen-independent human prostate cancer cells due to the absence of androgen receptor (AR) mRNA and protein expression at the transcriptional level as a result of epigenetic modification of AR." (PMID 25690296, 2015). "Castration-resistant prostate cancers still depend on nuclear androgen receptor (AR) function despite their lack of dependence on exogenous androgen." (PMID 25730905, 2015). "Prostate cancer cells expressing constitutively active, C-terminally truncated low molecular weight AR-species lacking the AR-ligand binding domain (LBD) has added another layer of complexity in the targeting." (PMID 25705125, 2015). "Androgen receptor (AR) directly regulates miR-21 by binding to the miR-21 promoter in prostate cancer; Siddiqui and coworkers (2011) demonstrated that EGCG inhibited prostate cancer cell growth by decreasing the level of AR and miR-21." (PMID 25853141, 2015). "The AR is a ligand-activated transcription factor that promotes prostate cancer growth through genomic and nongenomic actions." (PMID 25693800, 2015).
prostate carcinoma (continued). "Combined with previous finding that DACH1 represses ligand induced transcriptional activation of the androgen receptor and prostate cancer cellular proliferation in tissue culture, it is likely that DACH1 conveys distinct functions at different stages of prostate cancer onset and progression." (PMID 26682253, 2015). "However, in a variable time frame, prostate cancer becomes resistant to ADT, and cancer cells are able to reactivate and AR signalling." (PMID 25864518, 2015). "Numerous studies have shown that androgen receptor (AR)-mediated signaling plays an important role in the development of CRPC, which may render prostate cancer cells resistant to treatment." (PMID 29147414, 2015). "miR-101 is also expressed in AR negative prostate cancer cells, but at lower levels compared to AR positive cells." (PMID 26473737, 2015). "Western blot analysis was carried out on extracts from cells transfected with control, AR, and CXCR7 siRNAs, and the expression of PSA, a model androgen-regulated gene that serves as a surrogate marker of AR transcriptional activity in prostate-cancer cells, was monitored." (PMID 25884570, 2015). "In LNCaP prostate cancer cells transfected with a plasmid expressing AR, it has been reported that the IFI-16 protein product binds within the DBD of AR and down-regulates AR and AR target gene expression." (PMID 25997614, 2015). "In prostate cancer, RLN2/RXFP1 signaling increased cell migration and proliferation in androgen-receptor (AR)-dependent LNCaP and AR-independent PC3 prostate cancer cells and promoted growth in xenografts derived of androgen-independent PC3 prostate cancer cells." (PMID 26322020, 2015). "Obviously, interest has focused on the prostate because it is known that prostate cancer cells possess STS activity to desulfate DHEAS, followed by downstream conversion of DHEA to androstenedione resulting in androgen receptor (AR) activation." (PMID 26213785, 2015). "Given the broad spectrum of pathways regulated by PP2A it is feasible that those prostate cancers driven by MYC and AR may also benefit from therapies targeting endogenous regulators of PP2A." (PMID 26563471, 2015). "Interestingly, the administration of sorafenib increased the expression levels of the androgen receptor, p-GSK3β and p-ERK1/2 in castration-resistant prostate cancers." (PMID 25953027, 2015). "Drugs targeting androgen receptor are widely used in human pharmacotherapy, e.g. non-steroid antiandrogen flutamide for the treatment of prostate cancer." (PMID 25811655, 2015). "Further biochemical experiments will delineate whether AR and CXCR7 interact directly or indirectly in prostate-cancer cells." (PMID 25884570, 2015). "Ectopic expression of AR in AR-negative prostate cancer cells, or gain of function of the AR signaling in AR-positive cells, led to suppression of autophagy, demonstrating the negative role of AR in celastrol-induced autophagy in prostate cancer cells." (PMID 26473737, 2015). "We also did not observe effects on hormone-independent AR activity when β-catenin was overexpressed in wild type 22Rv1 prostate cancer cells, a system in which endogenous FKBP52 is present." (PMID 26207810, 2015). "In an androgen-insensitive prostate cancer PC-3 cell line not expressing AR but having ER-α, resveratrol induces reduction in ER-α with a maximum effect at 100–150 μM." (PMID 26456774, 2015). "Work described in this manuscript shows that the activity of the Wnt/β-catenin pathway is low in prostate cancer cells likely due to the preference for β-catenin interaction with AR rather than TCF4 in these cells." (PMID 26509262, 2015). "Thus, drugs that target FKBP52 proline-rich loop-AR BF3 interactions represent a novel and promising approach to prostate cancer therapy." (PMID 26207810, 2015). "Ectopic expression of AR in AR-negative prostate cancer cells, or gain of function of the AR signaling in AR-positive cells, led to suppression of autophagy." (PMID 26473737, 2015).
prostate carcinoma (continued). "We also showed that gal inhibits AR positive and negative prostate cancer cells suggesting involvement of additional targets." (PMID 26196320, 2015). "EBR decreased the CALR and CALNX expression profiles time-dependently by causing caspase-dependent apoptotic cell death in both AR-expressing and AR-non-expressing prostate cancer cells." (PMID 26353013, 2015). "In AR negative prostate cancer cells PC3, ceramide activates the protein phosphatase 2A (PP2A) and increased p27(kip1) protein levels via Akt-dependent and Akt-independent pathways, suggesting some overlaps in pathways influenced by lipid homeostasis." (PMID 26587537, 2015). "No change was observed in AR expression after Ex–4 and metformin treatment in the prostate cancer tumor." (PMID 26439622, 2015). "To determine the relationship between CX43 and AR pathway in prostate cancers, we detected the expression of CX43 in nonmalignant and malignant prostate cells after androgen stimulated in time course." (PMID 26491675, 2015). "In contrast, a reduction in RUNX1 expression, not overexpression, is required to prevent AR-independent growth inhibitory effect on prostate cancer cells." (PMID 25537508, 2015). "Currently however, we do not know how decreased stromal AR contributes to prostate cancer progression, or indeed how androgen action differs between prostate stromal and epithelial cells." (PMID 25965833, 2015). "While several studies independently linked increased invasion and metastasis with elevated AR or Src activity, the specific role of cytoplasmic AR signaling via Src to promote prostate cancer migration and invasion was not reported." (PMID 25730905, 2015). "In human prostate cancer cells, AR/miR-190a/YB-1 signaling forms an auto-regulatory negative feedback loop, where miR-190a contributes to the human prostate cancer cell growth through AR-dependent signaling." (PMID 26314494, 2015). "We observed similar findings in prostate cancer lines: ELK1-shRNA strongly inhibited AR-negative cell migration/invasion and MMP-2/MMP-9 expression (unpublished data)." (PMID 26342199, 2015). "We employed several different prostate cancer cell lines to demonstrate the universality of the nongenomic AR/Src invasion pathway." (PMID 25730905, 2015). "We have previously reported that ring-DIMs and DIM induce apoptosis and necrosis in androgen receptor-positive (AR+) AD LNCaP and in androgen receptor-negative (AR-) AI PC-3 prostate cancer cells." (PMID 26124925, 2015). "Thus we revealed the AR-miR-204-XRN1-miR-34a positive feedback loop and a dual function of miR-204/XRN1 axis in prostate cancer." (PMID 25797256, 2015). "In summary, our results demonstrate that AR plays a negative role of in the regulation of celastrol-induced autophagy; it suppresses autophagy via transactivation of miR-101 in prostate cancer cells." (PMID 26473737, 2015). "The ability of TPGS to induce apoptosis was also investigated in androgen receptor negative (AR−) DU145, PC3, and androgen receptor positive (AR+) LNCaP prostate cancer cells." (PMID 26137487, 2015). "Most aggressive prostate cancers express high levels of androgen receptor (AR) and, in addition, utilize a variety of mechanisms to activate AR in the absence of its ligand." (PMID 26010887, 2015). "Together, the data demonstrate that blockage of PI3K/mTOR pathway successfully suppress cell proliferation in both AR sensitive and non-sensitive prostate cancer cell lines." (PMID 26506516, 2015). "To determine whether these observations are relevant in context of in vivo human prostate cancer, we compared relative levels of T, DHT and AR expression in tumor metastases directly obtained from men with CRPC." (PMID 25356728, 2014).
prostate carcinoma (continued). "Early reports demonstrated that the AR degradation enhancer ASC-J9 could suppress AR-mediated diseases, such as liver cancer, bladder cancer, prostate cancer, and spinal and bulbar muscular atrophy." (PMID 24956378, 2014). "In prostate cancer, overexpression of NLK induced apoptosis in AR-expressing prostate cancer cells, but not in AR-negative cells." (PMID 24816797, 2014). "Besides, the watercress-derived phenethyl-isothiocyanate downregulated miRNA-141, which repressed the expression of the androgen receptor and the PSA level in prostate cancer cell lines." (PMID 25017900, 2014). "An important aspect of IGF signaling in prostate cancer development and progression is that it is able to activate androgen receptor nuclear translocation in the absence of androgen." (PMID 25089270, 2014). "Despite the long appreciation of the importance of targeting AR signaling for prostate cancer treatment, no therapy has been developed to date to target AR directly to reduce its availability." (PMID 25375370, 2014). "In this present study we show that AhR is constitutively active in advanced prostate cancer cells and that ablation of constitutive AhR signaling to inhibit androgen independent growth is not dependent on androgen receptor status." (PMID 24755659, 2014). "In addition, both AR and PPP1 undergo nuclear translocation when prostate cancer cells are stimulated by androgen." (PMID 24629090, 2014). "Chemical ablation of AhR signaling can reduce the growth of advanced prostate cancer cells, an effect not achieved with androgen receptor inhibitors or growth in androgen depleted media." (PMID 24755659, 2014). "The data presented here, reveals that AhR can modulate proliferation of prostate cancer cells in the absence of androgen receptor." (PMID 24755659, 2014). "Androgens play a key role in the development of normal healthy prostate tissue; however, androgen signaling and, specifically, the androgen receptor, also known as nuclear receptor subfamily 3, group C, member 4, (NR3C4), is the principle stimulant of prostate cancer progression." (PMID 25533015, 2014). "These compounds covalently bind to the AR AF-1 region to inhibit androgen-induced proliferation of LNCaP human prostate cancer cells at concentrations that do not block the proliferation of PC3 cells that do not express a functional AR." (PMID 25268119, 2014). "To investigate the effects of polyamides outside of AR-dependent transcription, we first compared the cytotoxicity of polyamides 1 and 2 in three different prostate cancer cell lines, LNCaP, LNAR and DU145, which express high, normal and low levels of AR, respectively." (PMID 25249630, 2014). "Two previous studies had reported that metformin treatment of prostate cancer cells down-regulates the expression of AR, though neither of them addressed potential effects on the expression of androgen-regulated genes." (PMID 25003216, 2014). "Moreover, shikonin treatment inhibited AR target gene expression, PSA and growth inhibition of prostate cancer cells." (PMID 24573652, 2014). "The important association between AR and PTEN has previously been demonstrated for prostate cancer but not tested for ovarian cancer." (PMID 25608477, 2014). "Recent considerations of actual therapy resistance include newly acquired mechanisms within the AR-axis under the individual treatment and do not necessarily require ultimate castration resistance as in AR-negative cell models of prostate cancer." (PMID 25332874, 2014). "In contrast to bicalutamide, it exhibits no agonist activity in prostate cancer cells that over express AR." (PMID 25062956, 2014). "The objective of this study was to test the ability of AUY922 to antagonize the transcriptional and/or protein stability of the AR in castrate resistant MYC-CaP/CR and Pten-CaP/cE2 prostate cancer cell lines as well as a transplant mouse model recently developed in our laboratory." (PMID 25072314, 2014).
prostate carcinoma (continued). "Our data showed that not all prostate cancer cell lines express the same subtype of potassium channel and we further found that minoxidil suppressed the growth of AR-expressing LNCaP cells in a concentration-dependent manner." (PMID 24742982, 2014). "Traditionally, investigations have primarily focused on the effects of targeting AR signaling in prostate cancer cells; however, ADT/ATT is not specific to tumor cells alone." (PMID 25566507, 2014). "The evidence is overwhelming that the androgen receptor is a valuable target for prostate cancer, however, an alternative strategy should be explored to disrupt the androgen receptor as opposed to traditional antagonists at the ligand binding domain." (PMID 24598693, 2014). "Inhibition of AR positive and negative prostate cancer cells by metformin suggests involvement of additional targets." (PMID 24484909, 2014). "If extrapolating from mechanisms observed in prostate cancer, is not surprising to identify a correlation between activated RTKs and the expression of the AR." (PMID 24779793, 2014). "In the current study, we examined the role of MID1 in AR signaling and the potential mechanisms by which MID1 may contribute to prostate cancer initiation and/or progression." (PMID 24913494, 2014). "This current study reveals AhR’s ability to modulate growth of prostate cancer cells independent of androgen receptor activity." (PMID 24755659, 2014). "Furthermore, activations of the AR, PI3K, mTOR, NFκB and Hedgehog (Hh) signaling pathways are involved in the fatal development of castration-resistant prostate cancer during androgen ablation therapy." (PMID 24913494, 2014). "In this study, we observed CAMK2N1 and AR signaling form an auto-regulatory negative feedback loop in human prostate cancer cells." (PMID 25296973, 2014). "Expression was also observed in two prostate cancer cell lines tested while significantly higher expression was observed in the more aggressive androgen receptor negative line, PC3." (PMID 24912876, 2014). "The prostate cancer cell line LNCaP and the molecular apocrine breast cancer cell line MDA-MB-453, which express high levels of AR, were used as positive controls for AR expression." (PMID 24451109, 2014). "However, treatment of prostate cancer cells with the analogue of 3,3'-diindolylmethane (BR-DIM) and curcumin inhibited AR/TMPRSS2-ERG/Wnt signaling." (PMID 24739220, 2014). "Additionally over-expression of AR and EZH2 appeared to be important to promote the progression of prostate cancer." (PMID 25535400, 2014). "Etoposide treatment dose-dependently inhibited AR-mediated cell growth, AR transcription, AR nuclei translocation, binding of androgen to AR, AR mRNA and protein expression level, and production of PSA in LNCaP prostate cancer cells." (PMID 24349321, 2013). "In a previous study, we investigated the short-term effects of dual targeting of the AR with the regulatory subunit type I alpha (RIα) of protein kinase A (PKA) in androgen sensitive (LNCaP) and castration-resistant (LNCaPabl) prostate cancer cell lines in vitro." (PMID 23736698, 2013). "Because of the controversial prognostic utility of TMPRSS2:ERG fusion in prostate cancer, we employed the strategy of a three-marker FISH panel to detect well documented prostate cancer DNA aberrations, including TMPRSS2/ERG rearrangements, AR copy number gain, and PTEN deletion." (PMID 24098661, 2013). "Both of these therapies become ineffective when prostate cancer recurs in a castration-resistant state and the AR neither depends on androgens nor is antagonized by anti-androgens (i.e. Bicalutamide), and the outcome is usually death." (PMID 23724033, 2013). "In addition, we also observed apoptosis of prostate cancer cell by blocking the MAPK/ERK, PI3K/Akt/mTOR, and Hsp90/AR pathways." (PMID 24130883, 2013). "In prostate cancer cells, EBP1 has been shown to suppress translation of androgen receptor mRNA." (PMID 23840586, 2013).